TLR7 (toll like receptor 7)
Diseases named in the same sentence as TLR7 in open-access papers (continued):
Sharing a sentence is not in itself a finding about the gene and the disease.
lupus (continued). "TLR7 agonism has the additional benefit of rapid onset of action, and is also being used as an accelerant in spontaneous lupus murine models." (PMID 31998321, 2019). "While the role of TLR7 in B cells has been extensively investigated in murine lupus, still much less is known about the TLR7 signaling in human SLE." (PMID 31231380, 2019). "This is unexpected because the disease phenotype of other lupus-prone mouse strains is prevented by crossing to TLR7 KO mice, whereas crossing to TLR9 KO mice has actually been reported to exacerbate lupus by causing the up-regulation of TLR7." (PMID 31694920, 2019). "Data from mouse lupus models support a B cell-intrinsic role of TLR7 signaling in B cell activation and the production of auto-Abs." (PMID 31231380, 2019). "Despite the fact that murine TLR8 does not seem to have a ligand, we previously demonstrated that it plays an important biological role by controlling TLR7-mediated lupus." (PMID 31552019, 2019). "While TLR7-stimulated lupus-prone mice demonstrated mild-moderate acceleration of autoimmunity, Type I IFN production and lupus nephritis, there was no change in renal function at the time of death." (PMID 31998321, 2019). "Topical TLR7 agonist treatment with R848 (resiquimod) significantly decreased survival in both WT B6 and lupus-prone NZM2410 mice compared to the acetone control groups." (PMID 31998321, 2019). "Epicutaneous treatment of mice with the Toll-like receptor 7 (TLR-7) agonist Resiquimod induces auto-antibodies and systemic tissue damage, including in the heart, and is used as an inducible mouse model of systemic lupus erythematosus (SLE)." (PMID 31324689, 2019). "Recently, another laboratory reported that crossing ABIN1 KO mice to either TLR7 KO mice or TLR9 KO mice had little effect on autoimmunity or glomerulonephritis and that crossing to TLR7/TLR9 double KO mice was required to prevent these hallmarks of lupus." (PMID 31694920, 2019). "The aggressive lupus-like phenotypes in the male are driven by a 2-fold increase in TLR7 expression due to the presence of the yaa locus." (PMID 31354711, 2019). "Lupus-like pathology can also be created by topical treatment of mice with TLR7 agonists like R837 (imiquimod) and R848 (resiquimod)." (PMID 31105556, 2019). "Two recent studies show an association between TLR7 rs3853839 G risk allele and the development of lupus nephritis or other manifestations of SLE, including malar rash, photosensitivity, pericardial effusion, reduced complement, and anti-dsDNA and anti-Sm auto-Abs." (PMID 31231380, 2019). "A recent study showed that the pathobiont Enterococcus gallinarum was able to translocate to the liver and activate autoantigenic T cells, induce IFN-responses through TLR7 stimulation and anti-dsDNA Ab production in lupus prone mice." (PMID 31354738, 2019). "TLR7 is known to play a critical role in the onset of lupus, yet studies reporting comparative expression at the protein level are limited." (PMID 31354711, 2019). "On the contrary, deletion of TLR7 inhibited the production of anti-ssRNA antibody and prevented lupus." (PMID 30286201, 2018). "Autoantibody production and glomerulonephritis in pristane-induced lupus require Toll-like receptor 7 (TLR-7)–mediated type I IFN production driven by the transcription factors IFN regulatory factor 5 (IRF-5) and IRF-73." (PMID 29463868, 2018). "The same research group subsequently demonstrated that the manifestations in TLR9−/− mice that showed exacerbated lupus symptoms depended on TLR7, and that TLR9 inhibited the autoantibody production that was dependent on TLR7." (PMID 30103522, 2018). "According to previous study, we initially applied imiquimod (IMQ), a TLR-7 agonist, to induce lupus mice." (PMID 29988544, 2018). "It was also demonstrated that Gal-9 inhibits TLR7/TLR9-mediated lupus in mouse models by modulating plasmacytoid DCs and B cells, and protects kidney from immune complex-induced damage." (PMID 30687334, 2018).
lupus (continued). "Our observations provide new insights about the MZ B cell translocation in lupus patients as well as the dichotomy of TLR9 and TLR7 signals in the pathogenesis of lupus." (PMID 30286201, 2018). "Mechanistically, the pristane model of lupus depends upon both the type I interferon receptor and toll-like receptor 7 for autoantibody formation and other aspects of the lupus phenotype." (PMID 29942314, 2018). "BKs suppressed important ISGs that we have previously shown to be induced upon TLR7 and -9 stimulation in lupus dendritic cells (DCs), especially the IRF7, a key regulator of Type I IFN responses." (PMID 29456540, 2018). "In the present study, we found that the significant expansion of MDSCs and severe podocyte injury in glomeruli of kidneys in toll-like receptor-7 (TLR-7) agonist imiquimod or pristane-induced lupus mice." (PMID 29988544, 2018). "In toll-like receptor-7 (TLR-7) agonist imiquimod-induced lupus mice, we found the severe podocyte injury in glomeruli of lupus mice and significant expansion of MDSCs in spleens and kidneys of lupus mice." (PMID 29988544, 2018). "TLR7 and TLR9 in particular have been implicated in the activation of autoreactive cells and antinuclear auto-Ab production in mouse models of lupus." (PMID 30323814, 2018). "Nineteen probes for 16 lupus-relevant genes (Abca1, Apobec3, Ccr7, Ceacam3, Ets1, Foxp3, Hdac1, Ifng, Irf9, Itgam, Jhdm1d, Mmp9, Oscar, Slc4a1, Tbx21, and Tlr7) were identified from the database of male murine spleen." (PMID 30246031, 2018). "Although generalization of our observations is limited by the nature of transgenic B cells, their different sensitivities to apoptotic cell associated antigens is consistent with the dichotomy of the TLR9 and TLR7 pathways observed in murine lupus." (PMID 30286201, 2018). "In in vivo analyses, the simultaneous presence of TGF-β and IL-10 effectively suppressed TLR-mediated antigen-specific immune responses and ameliorated pathologies in imiquimod (TLR7 agonist)-induced lupus model and lupus-prone MRL/lpr mice." (PMID 29963056, 2018). "Specific deletion of plasmacytoid dendritic cells in a murine TLR7-driven lupus model (Tlr7.Tg) or a polygenic model (B6.Sle1.Sle3) attenuates not only systemic autoimmunity but also lupus nephritis." (PMID 29650017, 2018). "Intrinsic B cell defects can directly contribute to the development of spontaneous GCs, breakdown of B cell tolerance and humoral autoimmunity, such as Tlr7 gene duplication or WAS (Wiskott–Aldrich syndrome) protein deficiency in lupus." (PMID 29559975, 2018). "In rheumatoid arthritis and systemic lupus erythematosus, hydroxychloroquine has been suggested to mediate its anti-inflammatory action by inhibiting the activation of TLR7 and TLR9 that reside in endosomal/lysosomal compartments." (PMID 30002366, 2018). "The exacerbation of disease in Tlr9-/- MRL.Faslpr was dependent on both Tlr7 and Ifnar1, suggesting that intact Tlr9 inhibits a proinflammatory signaling axis on the lupus-prone genetic background." (PMID 28278279, 2017). "We tested the ability of peripheral CD8+ T cells from lupus-prone mice to home to the brain by transferring five million purified CD45.1+ splenic TLR7[Tg] CD8+ T cells into CD45.2+ WT or TLR7[Tg] recipient mice." (PMID 28098193, 2017). "The pivotal role of TLR7 signalling in the pathogenesis of lupus was confirmed in several mouse models with the Y-chromosome-linked genomic-modifier Yaa in which there is duplication of the Tlr7 gene." (PMID 28456914, 2017). "In this respect, both TLR7 and TLR9 which initiate MYD88-dependent signalling pathways have been implicated in the pathogenesis of animal models of lupus and the production of anti-nuclear autoantibodies." (PMID 28456914, 2017). "The importance of the TLR7 pathway and the role of pDCs in lupus pathology have been suggested in animal studies and human genetic studies." (PMID 29052537, 2017).
lupus (continued). "A previous report demonstrated the benefits of BTK inhibition in mouse models of TLR7/IFN-driven lupus by affecting both BCR and FcR signaling." (PMID 28950886, 2017). "TLR9 rather ameliorates TLR7-dependent development of lupus-like disease by competing endosomal transport with TLR724." (PMID 28408984, 2017). "More studies are therefore needed to evaluate if a different regulatory mechanism exists for TLR7-mediated cytokine modulation in lupus pDCs." (PMID 27509492, 2016). "Taken together, these results indicate that macrophages in lupus mice displayed increased expression of TLR7, elevated death and enhanced autophagy." (PMID 27537524, 2016). "Similar protective effects were also observed in Tcf4-haplodeficient Tlr7 transgenic and B6.Sle1.Sle3 lupus models in which the pDCs were functionally impaired by suppressing the E2-2 transcription factor." (PMID 27509492, 2016). "It is possible that pDC in SLE patients and lupus-prone mice can still produce a normal level of IFNα through the TLR7 pathway." (PMID 27034965, 2016). "The production of type I IFN induced by TLR7 is believed to occur primarily in plasmacytoid dendritic cells, but recently, the role of B cells in the development of lupus dependent on TLR7 was considered essential." (PMID 27228057, 2016). "pDCs in lupus are constantly stimulated by TLR7/9 ligands, which are known to suppress miR-29b and miR-29c, allowing for upregulation of the target of these microRNAs, including Bcl-2." (PMID 27034965, 2016). "The second question is which TLR, TLR9, or TLR7 is critical for the role of pDC in lupus pathogenesis." (PMID 27034965, 2016). "In line with this, IL-1R8 was also protective in a model of hydrocarbon oil-induced lupus, in which it modulated TLR7-mediated activation of DCs and expansion of autoreactive lymphocyte clones." (PMID 27148268, 2016). "Our results indicate that Notch1-Hes-1 signaling controls TLR7-induced autophagic death of macrophage via regulation of P62 in mice with lupus." (PMID 27537524, 2016). "Studies have shown that the pathogenic role of TLR7 in lupus-prone mice is partially dependent on IFNα induction, and TLR9 on the contrary can regulate lupus progression by suppressing TLR7 signaling." (PMID 27034965, 2016). "DCs play a crucial role in the pathogenesis of lupus through IFN-α production upon TLR7-/TLR9 stimulation." (PMID 27232337, 2016). "To identify potential regulator(s) involved in the enhanced TLR7 response in lupus pDCs, we examined miRNA expression profiles upon R837 stimulation and compared between pre-symptomatic and symptomatic mice." (PMID 27509492, 2016). "In particular, immune complexes containing the lupus autoantigen U1snRNP or nucleosomes activate DCs and autoreactive B cells via TLR7 and TLR9, respectively." (PMID 27148268, 2016). "Survival signal in pDC from both humans and lupus-prone mice is activated by TLR7/9-induced NFκB pathway." (PMID 27034965, 2016). "The hyper-responsiveness to TLR7 stimulation in BM-derived pDCs in symptomatic lupus-prone mice likely represents one of the pathological attributes for SLE development." (PMID 27509492, 2016). "The aim of this study was to analyze the pDC phenotype and its IFNα-producing ability by following Tlr7 and Tlr9 stimulation in different lupus-prone mouse strains." (PMID 26879679, 2016). "At last, we generated a TLR7 agonist-induced lupus mouse model, and confirmed that Notch-Hes-1 axis controlled TLR7-mediated autophagic death of macrophages via induction of P62." (PMID 27537524, 2016). "Accumulating evidence implicates TLR7-driven type I interferon (IFN-I) production as a key mediator of murine lupus." (PMID 26717913, 2015). "TLR7 was found to be essential for producing type I interferon and the development of lupus symptoms in an induced SLE model." (PMID 25927578, 2015).
lupus (continued). "Age-associated B cells (ABCs), which lack CD21 and CD23 expression but express myeloid cell-specific markers, are stimulated by TLR7 activation and have an increased presence in lupus-prone mice." (PMID 26528288, 2015). "Their involvement in SLE became apparent by the finding that disease severity in lupus-prone mouse models like the MRL-Faslpr strain was reduced by deletion of TLR7." (PMID 25695778, 2015). "As IFN-I plays a key role in pristane-induced lupus, we examined its effects on Tlr7 expression in B cells." (PMID 26717913, 2015). "In contrast, both anti-Sm/RNP and anti-dsDNA autoantibodies are TLR7-dependent in pristane-induced lupus." (PMID 26029213, 2015). "Although there were differences in the naïve repertoire between the chimeras it was not possible to distinguish a clear pattern of selection against lupus related autoreactivity in TLR7-/Yaa or female chimeras." (PMID 25794167, 2015). "A recent report using anti-CL/DNA autoantibody 3H9.GFP transgenic mice in lupus-prone NZW/BXSB background has determined the role of TLR7 signal in the differentiation of autoreactive (3H9) B cells." (PMID 26068236, 2015). "The Toll-like receptor 7 (TLR7), located at Xp22.2, has recently been determined to be associated with increased risk for lupus in males in Chinese and Japanese populations when a SNP is found in the 5′ untranslated region (UTR) of the gene." (PMID 25763008, 2015). "Very interestingly, it is now apparent that hydroxychloroquine, a mainstay in lupus treatment, is a TLR-7 and TLR-9 antagonist." (PMID 26579125, 2015). "Consistently, translocation of TLR7 to the Yaa locus accelerated systemic autoimmunity in another murine lupus model." (PMID 25927578, 2015). "Further normalization of TLR7 expression in B cells is found to rescue the severe lupus phenotypes in Sle1Tg7 mice." (PMID 26068236, 2015). "Similar to Tlr7-tg, Tcf4 haplodeficiency effectively blocked the development of lupus, as indicated by the significantly reduced anti-DNA antibody levels and glomerulonephritis." (PMID 26528288, 2015). "Increased expression and activation of TLR7 and TLR9 has previously been implicated in autoimmune diseases such as systemic lupus erythematosus (SLE) in BXSB and other lupus prone Yaa mice, which have a Tlr7 duplication, and in humans." (PMID 25229618, 2014). "Studies have shown that these mice have disparate T cell requirements of two subsets of lupus-specific autoantibodies as well as the toll-like receptor 7 (TLR7)-dependent and FcγR-independent production of type I interferon." (PMID 25501752, 2014). "Among the duplicated genes is Tlr7, which is necessary and sufficient for Yaa-mediated disease acceleration: Tlr7 deletion from the X chromosome abrogates Yaa-induced lupus phenotypes." (PMID 25147296, 2014). "It is also possible that the lesions in the huTLR7/8 BAC mice are distinct from those seen in lupus prone strains of mice with Tlr7 overexpression or in humanized TLR8 mice because they result from a neoplastic rather than an inflammatory process." (PMID 25229618, 2014). "As LMP1 is known to prime cells to express IFN, and both TLR7 and IFNs are believe to be involved in the development of systemic lupus erythematosus (SLE, or simply “lupus”), the association of EBV infection and autoimmunity clearly warrants further investigation." (PMID 25101093, 2014). "TLR7 deficient lupus prone mice on the other hand show less autoantibodies and less severe disease in both the MRL/lpr model and a transgenic lupus model." (PMID 24086313, 2013). "Gene duplication in TLR7 is sufficient, on its own, to generate an autoimmune disease that is similar to lupus." (PMID 23426937, 2013). "Treatment of lupus-prone mice with a dual inhibitor of TLR7 and TLR9 leads to the reduction of autoantibody production and disease activity." (PMID 23497717, 2013). "In support, lupus-prone mice that are transgenic for TLR7.1 and have excessive levels of TLR7 have more autoantibodies and early severe lupus." (PMID 24062747, 2013).
lupus (continued). "Tir8/Sigirr protected from hydrocarbon oil-induced lupus by suppressing the TLR7-mediated activation of DCs and expansion of IgG and RNA autoreactive lymphocyte clones." (PMID 23112799, 2012). "Treatment of lupus-prone mice with a dual inhibitor of TLR-7 and TLR-9 was found to lead to the reduction of autoantibody production and amelioration of disease symptoms." (PMID 22312407, 2012). "IL-6 production in lupus is reported to mediate by immune complexes that transmit signals through TLR7 and 9 and Fcγ receptor." (PMID 23140401, 2012). "IRS 954 (DV-1709) is a specific inhibitor of TLR7 and 9 that reduced serum levels of nucleic acid-specific antibodies, and reduced end-organ damage in a lupus murine model." (PMID 23151919, 2012). "For subjects with HPV infection, levels of TLR3 and TLR7 were significantly lower in lupus patients compared with controls." (PMID 22513098, 2012). "For subjects with HPV infection (Groups 1 and 3), TLR3 and TLR7 levels were significantly lower in lupus patients compared with controls." (PMID 22513098, 2012). "Some TLR7-deleted lupus-prone mice strains have decreased lymphocyte and pDC activation, decreased serum IgG, and ameliorated autoimmune disease." (PMID 22110541, 2012). "It has been shown that lupus was initiated by a translocation of 17 genes, including TLR7, from the X to the Y chromosome." (PMID 22761632, 2012). "Inhibition of TLR7 reduces anti-RNA autoantibody production, glomerular IgG levels and glomerular macrophage infiltration and thus attenuates glomerulonephritis in lupus mice and represents a potential therapeutic target in lupus." (PMID 21818370, 2011). "In dendritic cells, TLR9 (and TLR7) activation induces among others high levels of type I IFN, a cytokine heavily implicated in the pathogenesis of Systemic Lupus Erythematosus and Sjögren's syndrome." (PMID 20490286, 2010). "Other explanations are also possible, including selective effects of palindromic INH-ODNs on TLR7 activation, as TLR7 plays a well-proven role in the pathogenesis of MRL-Fas lpr/lpr lupus." (PMID 20490286, 2010). "Literature search shows that classes B and G INH-ODNs and combined TLR7/9 inhibitors are effective in animal models of lupus." (PMID 20490286, 2010). "This lupus strain harbors a duplication of the TLR7 gene which appears to be responsible for the phenotype." (PMID 19476613, 2009). "While TLR7-/- MRL-Faslpr/lpr lupus mice have better survival, they still succumb to autoimmune disease, thus suggesting a possible role for additional DNA/RNA-triggered intracellular signaling pathways (for example, DAI and RIG-I)." (PMID 19476613, 2009). "Lupus‐like phenotypes can be ameliorated by deletion of Tlr7 in various lupus mouse models." (PMID 41574968, 2026). "In addition to resolving why TLR7 signals drive more severe lupus, our results have implications for fundamental TLR biology." (PMID 40794441, 2025). "Therefore, enhanced TLR7 signaling in lupus mice likely amplifies neuronal activity and promotes spinal central sensitization by increasing the production and release of IL-1β and IL-18." (PMID 41511304, 2025). "The role of TLR7 was demonstrated in a mouse lupus model BXSB male mice." (PMID 40710333, 2025). "Recently, several mutations of the human Unc93b that enhance TLR7 but not TLR9 activity were shown to mediate a rare form of genetically mediated pediatric lupus." (PMID 40794441, 2025). "Neuronal shrinkage and nuclear chromatin condensation were visible in the hippocampal cornu ammonis and dentate gyrus zones of lupus mice, with an increased expression of TLR7 and NLRP3, versus significantly less neurodegeneration and TLR7 and NLRP3 expression in the CLC group." (PMID 40507090, 2025). "Altogether, these results suggest that preventive cinnamon supplementation protects the BBB from disruption in TLR7-induced lupus; this protection may also mediate cinnamon’s positive effect on behavior and brain histology." (PMID 40507090, 2025).